ELOVL7 (ELOVL fatty acid elongase 7)
Description:
Catalyzes the first and rate-limiting reaction of the four reactions that constitute the long-chain fatty acids elongation cycle. This endoplasmic reticulum-bound enzymatic process allows the addition of 2 carbons to the chain of long- and very long-chain fatty acids (VLCFAs) per cycle. Condensing enzyme with higher activity toward C18 acyl-CoAs, especially C18:3(n-3) acyl-CoAs and C18:3(n-6)-CoAs. Also active toward C20:4-, C18:0-, C18:1-, C18:2- and C16:0-CoAs, and weakly toward C20:0-CoA. Little or no activity toward C22:0-, C24:0-, or C26:0-CoAs. May participate in the production of saturated and polyunsaturated VLCFAs of different chain lengths that are involved in multiple biological processes as precursors of membrane lipids and lipid mediators.
Synonyms: FLJ23563
Tractability: Small molecule: a structure with a bound ligand is known. Antibody: UniProt predicts a signal peptide or a membrane-spanning region. PROTAC: ubiquitination databases record sites on it.
Target class: Enzyme; Transferase
Gene: Protein-coding gene on chromosome 5 (60,751,791 to 60,844,274, reverse strand). Ensembl gene ENSG00000164181.
Subcellular location: Endoplasmic reticulum membrane
Pathways (Reactome):
Metabolism: Synthesis of very long-chain fatty acyl-CoAs
Gene Ontology:
Molecular function: fatty acid elongase activity; protein binding
Biological process: fatty acid elongation, polyunsaturated fatty acid; fatty acid elongation, saturated fatty acid; very long-chain fatty acid biosynthetic process; fatty acid elongation, monounsaturated fatty acid; long-chain fatty-acyl-CoA biosynthetic process; sphingolipid biosynthetic process; fatty acid biosynthetic process; fatty acid elongation; unsaturated fatty acid biosynthetic process
Cellular component: endoplasmic reticulum; endoplasmic reticulum membrane; membrane
Genetic constraint (gnomAD): Loss-of-function variants: 17 observed, 24.63 expected, observed/expected ratio (o/e) 0.69, 90% interval 0.47 to 1.03. The upper end of that interval is the gene's LOEUF score, 1.03, which puts it in group 4 of 6, group 1 being the genes least tolerant of losing a copy. Missense variants: 267 observed, 293.36 expected, observed/expected ratio (o/e) 0.91, 90% interval 0.82 to 1.01. Synonymous variants: 89 observed, 101.37 expected, observed/expected ratio (o/e) 0.88, 90% interval 0.74 to 1.05.
Homologues: Orthologues: chimpanzee ELOVL7 (99% identical), macaque ELOVL7 (97% identical), dog ELOVL7 (92% identical), pig ELOVL7 (90% identical), mouse Elovl7 (89% identical), rat Elovl7 (88% identical), guinea pig ELOVL7 (83% identical), rabbit ELOVL7 (82% identical), tropical clawed frog elovl7 (75% identical), zebrafish elovl7a (65% identical), Drosophila melanogaster CG31522 (49% identical), Drosophila melanogaster Elovl7 (48% identical), and 14 more. Paralogues in human: ELOVL1 (57% identical), ELOVL4 (44% identical), ELOVL2 (40% identical), ELOVL5 (36% identical), ELOVL6 (26% identical), ELOVL3 (22% identical).
Diseases named in the same sentence as ELOVL7 in open-access papers:
ELOVL7 is named in the same sentence as 32 diseases in open-access papers, as found by Europe PMC text mining. Sharing a sentence is not in itself a finding about the gene and the disease. The quoted sentences say what the papers report.
prostate carcinoma (10 papers, 2016 to 2025). A carcinoma that arises from epithelial cells of the prostate gland. "Our study also suggests a potential role for elongases in tumor-induced angiogenesis, as overexpression of ELOVL7 has been linked to prostate cancer and is required for cancer growth." (PMID 40236168, 2025). "ELOVL7 has been identified as a crucial player in the lipid metabolism associated with prostate cancer growth." (PMID 40542303, 2025). "The study also provided evidence that ELOVL7 preferentially elongates saturated very-long-chain fatty acids (SVLFAs), which are implicated in lipid metabolism and androgen synthesis within prostate cancer cells." (PMID 40542303, 2025). "Outside the context of infection, ELOVL7 is expressed in many tissues, with the highest levels in the pancreas and prostate, and its overexpression is associated with prostate cancer." (PMID 33947752, 2021). "The results showed a specific reduction of saturated very-long-chain fatty acids (SVLFA C20:0, C22:0, C24:0), indicating that ELOVL7 plays a significant role in regulating lipid profiles in prostate cancer cells." (PMID 40542303, 2025). "Their research demonstrated that the knockdown of ELOVL7 markedly reduced prostate cancer cell growth, while a high-fat diet significantly promoted tumor growth in ELOVL7-expressing prostate cancer models." (PMID 40542303, 2025). "The lipogenic enzyme ELOVL7 is overexpressed in prostate cancer cells; however, the impact of its mediated fatty acid elongation process on the activation of the NF-κB pathway by SFAs requires further investigation." (PMID 40542303, 2025). "In prostate cancer, knockdown of ELOVL7 reduced saturated fatty acids in membrane glycerophospholipids but also reduced the levels of cholesterol, the critical precursor of the androgen hormones that drive prostate cancer growth." (PMID 33413672, 2021). "The minor change of these two FAs after overexpression of ELOVL7 agrees with data from prostate cancer cells." (PMID 31242694, 2019). "ELOVL6 is overexpressed in NASH-associated hepatocellular carcinoma and in acute myeloid leukemia, while ELOVL7 is overexpressed in prostate cancer cells." (PMID 26862848, 2016). "In earlier reports it has been shown that silencing of ELOVL1 reduced cell viability of breast cancer cells significantly and that inhibition of ELOVL7 resulted in drastic attenuation of prostate cancer cell growth." (PMID 26862848, 2016). "When compared to cells on a normal diet (ND), those exposed to an HFD exhibited a differential growth pattern, suggesting that HFD may promote the growth of ELOVL7-expressing prostate cancer cells." (PMID 40542303, 2025). "Collectively, while the statistical significance of the effect of HFD on the growth of these prostate cancer cells is not highly conclusive in this study, the observed trend, combined with the known role of ELOVL7 in lipid metabolism and prostate cancer progression, provides valuable insights." (PMID 40542303, 2025). "For instance, after knocking out the ELOVL7 gene in prostate cancer cells and subsequently exposing them to SFAs, the effects on NF-κB activation and tumorigenesis can be observed to determine the necessity of ELOVL7 in SFA-mediated NF-κB activation and tumorigenesis." (PMID 40542303, 2025). "Additionally, ELOVL7 has been identified as a crucial factor in lipid metabolism related to prostate cancer growth, influencing both fatty acid composition and androgen synthesis." (PMID 40542303, 2025). "Notably, the lipogenic gene ELOVL7, which is overexpressed in prostate cancer cells, has emerged as a crucial factor in understanding the metabolic reprogramming related to fatty acid metabolism." (PMID 40542303, 2025). "It was reported that ELOVL7 was involved in prostate cancer growth." (PMID 38965225, 2024).
prostate carcinoma (continued). "ELOVL7 plays a crucial role in cancer cell migration and metastasis in prostate cancer, which involves in prostate cancer growth and survival through the metabolism of SVLFAs saturated very-long-chain fatty acids (SVLFA, C20:0 approximately) and their derivatives." (PMID 37981715, 2023). "Knockdown of ELOVL7 in prostate cancer cell lines resulted in reduced levels of saturates FA." (PMID 31242694, 2019). "ELOVL7 was reportedly involved in prostate cancer growth via controlling the synthesis of LCFA." (PMID 31242694, 2019). "In a follow-up analysis, ELOVL7’s role in altering lipid profiles and its connection to de novo androgen synthesis were further elucidated, indicating that ELOVL7 could be a pivotal target for therapeutic strategies aimed at mitigating prostate cancer progression via dietary interventions." (PMID 40542303, 2025). "There is one study where in the human prostate cancer cell line (LNCaP) with the knockdown of ELOVL2, ELOVL5, or ELOVL7, no compensatory increases in the expression of the other ELOVLs were observed in the cancer cell line, and no normal cell line was analyzed." (PMID 38139442, 2023).
Parkinson disease (4 papers, 2018 to 2022). A progressive degenerative disorder of the central nervous system characterized by loss of dopamine producing neurons in the substantia nigra and the presence of Lewy bodies in the substantia nigra and locus coeruleus. "ELOVL7 is also expressed in the brain, and a decrease in its expression correlates with Parkinson's disease." (PMID 33947752, 2021).
HCMV infection (2 papers, 2017 to 2021). "Furthermore, ELOVL7 is the one of the ELOVLs associated with the synthesis of elongation of very long FAs, revealing an association between metabolism and HCMV infection." (PMID 28993767, 2017). "We previously demonstrated that HCMV infection with AD169 increases ELOVL7 gene expression and that protein levels start to increase by 48 hpi and remain elevated from 72 to 120 hpi." (PMID 33947752, 2021). "Similarly, HCMV infection increases ELOVL7 at 48 to 96 hpi, and lipid changes, including the increases in DG, TG, and PL lipids, occur as early as 48 hpi and continue to be promoted through 96 hpi." (PMID 33947752, 2021). "Using AD169, we previously demonstrated that HCMV infection increases ELOVL5 and ELOVL7 transcripts, ELOVL7 protein levels, FA elongation, VLCFA synthesis, the abundance of PLs with SFA/MUFA tails, and the levels of PERK protein." (PMID 33947752, 2021). "We conclude that PERK is necessary for HCMV infection-related increases in ELOVL7, but not ELOVL5, protein levels." (PMID 33947752, 2021). "Following HCMV infection, PERK regulates lipid metabolism by promoting ELOVL7, but not ELOVL5." (PMID 33947752, 2021).
alcohol dependence (1 paper, 2023). Physical and psychological dependence on alcohol. "We observed that the ELOVL7 exon skipping event exhibits greater significance for the association with the problematic alcohol use traits of alcohol dependence, AUD, and AUDIT-P, compared to the alcohol consumption trait of drinks per week (DrnkWk)." (PMID 37217680, 2023). "Of note, ELOVL7, was previously identified as down-regulated in prefrontal cortex in individuals with alcohol dependence." (PMID 37217680, 2023).
alcohol use disorder (1 paper, 2024). "This is exemplified by exon skipping events in key genes like ELOVL7, which can elevate the risk of alcohol use disorder." (PMID 38396082, 2024).
amyotrophic lateral sclerosis (1 paper, 2024). Amyotrophic lateral sclerosis (ALS) is a neurodegenerative disease characterized by progressive muscular paralysis reflecting degeneration of motor neurons in the primary motor cortex, corticospinal tracts, brainstem and spinal cord. "A more comprehensive analysis indicates that upregulated proteins (ELOVL5, ELOVL7, TECR, HSD17B4, ACSL1, HACD2, and CBR4) are significantly enriched within the pathways of oxidative phosphorylation and metabolic pathways pertinent to amyotrophic lateral sclerosis." (PMID 39335340, 2024).
gastric cancer (1 paper, 2025). A primary or metastatic malignant neoplasm involving the stomach. "Although a key enzyme Elovl5 promoting ferroptosis in gastric cancer cells, was no increase in expression, another elongase Elovl7 was increased, which catalyzes the rate-limiting step in the synthesis of very long-chain fatty acids and exhibits the highest activity toward 18-carbon fatty acids." (PMID 41285716, 2025).
glioma (1 paper, 2022). A benign or malignant brain and spinal cord tumor that arises from glial cells (astrocytes, oligodendrocytes, ependymal cells). "On the other hand, the expression level of ELOVL7, the third enzyme responsible for long-chain SFA elongation, does not affect the prognosis for patients with GBM or glioma." (PMID 36291290, 2022).
glomerular disease (1 paper, 2025). "Our snRNA-seq approach enabled identification of disease-specific podocyte subpopulations, revealing that the ELOVL7 → LC-PUFA → ACSL4 axis constitutes a previously unrecognized pathway driving podocyte vulnerability to lipid peroxidation and glomerular disease progression." (PMID 41285716, 2025).
Glomerular sclerosis (1 paper, 2025). Accumulation of scar tissue within the glomerulus. "Moreover, the levels of albumin-to-creatinine ratio (ACR) and glomerular sclerosis induced by ADR were attenuated in Elovl7 conditional knockout mice." (PMID 41285716, 2025).
lipid metabolic disorders (1 paper, 2024). "The reduction and inactivation of STAT3 lead to lipid metabolic disorders and promote triglyceride accumulation by upregulating the mRNA levels of ELOVL7, PPARG, MMP1, MMP13, and TIMP4, and downregulating the mRNA level of PTGS2." (PMID 39125712, 2024).
multiple system atrophy (1 paper, 2018). Multiple system atrophy (MSA) is a neurodegenerative disorder characterized by autonomic failure (cardiovascular and/or urinary), parkinsonism, cerebellar impairment and corticospinal signs with a median survival of 6-9 years. "Recent studies also indicated that ELOVL7, with the help of GWAS, was associated with multiple system atrophy." (PMID 30618709, 2018).
nephrotic syndrome (1 paper, 2025). A collection of symptoms that include severe edema, proteinuria, and hypoalbuminemia; it is indicative of renal dysfunction. "In the Nephrotic Syndrome Study Network (NEPTUNE) database, LPCAT3, ELOVL7 and FADS2 were all negatively associated with eGFR and positively associated with creatine and urea nitrogen." (PMID 41285716, 2025).
neuropathy (1 paper, 2021). A disorder affecting the nervous system that manifests with pain, tingling, numbness, and/or muscle weakness. "The presence of neuropathy in our cohorts is associated with variants in the ELOVL7 and NDUFAF2 genes that are located in the same region on chromosome 5." (PMID 33935957, 2021). "SNP rs2694528 in NDUFAF2, which is near ELOVL7, is associated with the presence of neuropathy." (PMID 33935957, 2021).
Obesity (1 paper, 2021). Accumulation of substantial excess body fat. "Due to high species conservation, the identified genes related to human or mice obesity traits may hold importance for adipose deposition in chickens, such as ELOVL7, IL6ST, IQGAP2, PAX5 and CKMT2." (PMID 34058970, 2021).
psoriasis (1 paper, 2015). An autoimmune condition characterized by red, well-delineated plaques with silvery scales that are usually on the extensor surfaces and scalp. "All other DEGPs could be placed along a continuum, with some showing greater psoriasis specificity (e.g., DBI, GLTP, HRNR, KRT73, ELOVL7), and others showing similar expression shifts in many or most skin diseases (e.g., MX1, S100A8, S100A9, STAT1, LAP3)." (PMID 26251673, 2015).
Stroke (1 paper, 2025). Sudden impairment of blood flow to a part of the brain due to occlusion or rupture of an artery to the brain. "Specifically, PPARα KO led to increased expression levels of Gadd45b, Nppa, Hdc, Lcn2, Il6, Sox4, Marcksl1, Saa3, Ucn2, Met, Dusp10, Elovl7, Ngf, C3, Il11, Hmox1, Alox5, Tnfsf9, Angptl4, Plin2, H19, Csf2rb, Atf3, and Col7a1 following stroke." (PMID 40362325, 2025).
cancer (8 papers, 2013 to 2025). A tumor composed of atypical neoplastic, often pleomorphic cells that invade other tissues. "It is plausible that ELOVL7 is upregulated in various tissues in cancer patients, indicating additional tissue targets for anti-angiogenic therapies." (PMID 40236168, 2025). "The implications of dietary fat and ELOVL7 expression extend beyond mere cancer cell growth; they also encompass metabolic pathways that influence androgen synthesis." (PMID 40542303, 2025). "This suggests that lipid metabolism, specifically the metabolism of saturated very - long - chain fatty acids (SVLFAs) by ELOVL7, plays a role in prostate carcinogenesis, emphasizing the link between dietary fat intake and cancer development.." (PMID 40542303, 2025). "In carcinoma cell lines, the finding that knockdown of ELOVL7 reduced saturated LCFA content and dramatically attenuated cell growth, provides direct evidence for the role of ELOVL7 in controlling cellular signaling." (PMID 31242694, 2019). "This suggests that ELOVL7 not only contributes to cancer cell proliferation but may also mediate the effects of dietary fat intake on prostate carcinogenesis." (PMID 40542303, 2025). "The NF-κB pathway is known to be involved in various aspects of cancer development; however, the exact mechanisms by which dairy products, Biseugenol B, and ELOVL7 interact with this pathway remain unclear." (PMID 40542303, 2025). "Additionally, the role of the lipogenic enzyme ELOVL7 is explored, emphasizing its involvement in fatty acid metabolism and cancer progression." (PMID 40542303, 2025). "Similarly, ELOVL6 and ELOVL7 have been reported to be overexpressed in various tumors and contribute to cancer progression." (PMID 40552308, 2025). "In terms of clinical implications, drugs that target ELOVL7 - mediated fatty acid elongation could potentially disrupt the abnormal lipid metabolism in cancer cells, thereby inhibiting tumor growth." (PMID 40542303, 2025). "ELOVL7, PTDSS1, POLR1D, TBC1D22A, CCNC and TCF25 are some of the interesting genes with cancer related functions identified from the DES analysis." (PMID 24088394, 2013).